NFKB1 (nuclear factor kappa B subunit 1)
Diseases named in the same sentence as NFKB1 in open-access papers (continued):
Sharing a sentence is not in itself a finding about the gene and the disease.
membranous glomerulonephritis (15 papers, 2016 to 2025). A slowly progressive inflammation of the glomeruli characterized by immune complex deposits at the glomerular basement membrane, resulting in a thickened membrane, and nephrotic syndrome. "Furthermore, in cultured human podocytes, TWEAK increased the expression of PLA2R as well as the expression of other genes recently identified by GWAS as linked to membranous nephropathy: NFKB1 and IRF4." (PMID 32664235, 2020).
Behçet’s disease (14 papers, 2012 to 2026). "Patients with Behcet’s disease and pyoderma gangrenosum have been reported to harbor somatic mutations in NFKB1 that modulate IL-1β production." (PMID 36355435, 2023). "Febrile attacks and small‐vessel vasculitis characteristic of Behçet syndrome may be caused by loss‐of‐function mutations in NFKB1, resulting in NF‐κB1 deficiency." (PMID 39964335, 2025). "In Behçet syndrome, rare variants in TNFAIP3, RELA, and NFKB1 genes have been identified, underscoring the importance of NF‐κB overactivation." (PMID 39964335, 2025).
dilated cardiomyopathy (14 papers, 2009 to 2025). Cardiomyopathy which is characterized by dilation and contractile dysfunction of the left and right ventricles. "Recently, a promoter polymorphism associated with a lesser activation of the NFKB1 gene was also associated with Dilated Cardiomyopathy." (PMID 20534156, 2010). "The main goal of the present investigation was to investigate the NFKB1 -94 insertion/deletion ATTG polymorphism in relation to risk of dilated cardiomyopathy (DCM)." (PMID 19480714, 2009).
systemic sclerosis (14 papers, 2010 to 2025). A chronic disorder, possibly autoimmune, marked by excessive production of collagen which results in hardening and thickening of body tissues. "Specifically, SNPs located within the promoter region of the NFKB1 gene, namely rs230534, rs4648133, and rs1599961, have demonstrated associations with systemic sclerosis in European, Turkish/Iranian, and Chinese Han populations." (PMID 38790215, 2024).
combined immunodeficiency (13 papers, 2015 to 2025). A broad classification of inherited disorders presenting at birth that affect both the cell-mediated and humoral aspects of the immune response. "Underlying diagnoses were IL12RB1 deficiency, NFKB1 haploinsufficiency, IFNGR1 deficiency, GATA2 haploinsufficiency, Kabuki syndrome, NEMO deficiency, and undefined combined immunodeficiency (CID)." (PMID 30984189, 2019).
kidney cancer (13 papers, 2010 to 2024). Primary or metastatic malignant neoplasm involving the kidney. "Furthermore, the activation of the NFKB1‐MYC link in FBW7‐deficient cells seems to sensitize them to Sorafinib (a MEK‐Raf inhibitor), a drug used in treatment of primary kidney cancer." (PMID 33502086, 2021).
acute coronary syndrome (12 papers, 2012 to 2026). Signs and symptoms related to acute ischemia of the myocardium secondary to coronary artery disease. "The objective of this study was to explore the potential interaction between the NFKB1-94ins/delATTG promoter polymorphism and general, abdominal, and gluteofemoral obesity in relation to the risk of incident acute coronary syndrome (ACS) in three large independent cohorts." (PMID 23671649, 2013). "RR* with 95% confidence interval in brackets for the combined effect of abdominal obesity and the NFKB1-94ATTG polymophism in relation to acute coronary syndrome." (PMID 23671649, 2013). "RR* with 95% confidence interval in brackets for the combined effect of gluteofemoral obesity and the NFKB1-94ATTG polymophism in relation to acute coronary syndrome." (PMID 23671649, 2013).
lymphoid neoplasm (12 papers, 2009 to 2024). A neoplasm composed of a lymphocytic cell population which is usually malignant (clonal) by molecular genetic and/or immunophenotypic analysis. "This miRNA, by affecting the NFKB1 pathway, participates in the inflammatory response, and also affects the development of myeloid and lymphoid tumors." (PMID 34356523, 2021).
uveal melanoma (12 papers, 2012 to 2024). A melanoma derived from melanocytes of the uveal tract. "NFkB (NFKB1) and COX-2 (PTGS2), known as inflammation-related molecules associated with a bad prognosis of Uveal melanoma, were highly expressed mainly in the macrophage population." (PMID 35525921, 2022).
gastric atrophy (11 papers, 2010 to 2025). "Nfkb1−/− mice showed enhanced gastric atrophy, with 62% parietal cell loss (P<0.05)." (PMID 23975431, 2013). "Nfkb1−/− mice developed more severe gastric atrophy than wild-type (WT) mice 6 weeks after H. felis infection." (PMID 28726772, 2017). "To determine whether Nfkb1−/− mice also developed spontaneous gastric atrophy, we quantified mean mucosal thickness and parietal cell number." (PMID 23975431, 2013). "Mice lacking NFKB1 (Nfkb1−/−) develop gastric atrophy of greater severity than wild-type mice." (PMID 34440074, 2021).
glucose metabolism disorders (11 papers, 2016 to 2025). "In addition, studies on epigenetic biological correlations related to inflammation, oxidative stress, and glucose metabolism disorders have found that the expression of NFKB1 and TIGAR genes is upregulated in visceral fat cells of obese patients with intermittent or chronic hyperglycemia." (PMID 40508108, 2025).
helminth infection (11 papers, 2011 to 2025). "Nfkb1−/− KO mice are more prone to bacterial and helminth infections, develop spontaneous inflammations and chronic inflammatory conditions, and show reduced numbers of myeloid progenitor cells and plasmacytoid dendritic cells." (PMID 38593810, 2024).
dysplasia (10 papers, 2013 to 2024). A usually neoplastic transformation of the cell, associated with altered architectural tissue patterns. "Generally the NFKB1 mRNA levels were significantly lower in tissues from cancer patients but unaffected in individuals with dysplasia." (PMID 23977225, 2013).
neuritis (10 papers, 2018 to 2025). A neuropathy arising from inflammation of one or more nerves. "SB216763 inhibits the activity of GSK3β and reduces the nuclear activity of the NFKB1 pathway, which alleviates neuritis." (PMID 36290175, 2022).
pterygium (10 papers, 2015 to 2025). A wedge-shaped fibrovascular lesion arising from the bulbar conjunctiva and extending to the cornea. "This study has indicated a significant association between expressions of inflammatory-related NFκB1, NFκB2 and RELA genes, and pterygium." (PMID 31565648, 2018). "In this study, we evaluated the probable associations between the mean expression levels of NFκB1, NFκB2 and RELA genes in the pterygium." (PMID 31565648, 2018). "Mean expression levels of NFκB1, NFκB2 and RELA genes were 2.4±0.3, 1.9± 0.5, and 1.8±0.4 times higher in patients with pterygium in comparison with controls, respectively." (PMID 31565648, 2018). "We examined the changes in expression of 3 inflammatory related NFκB1, NFκB2, and RELA genes in patients with pterygium." (PMID 31565648, 2018). "Hence, we evaluated the expression levels of three main genes of NFκB family including NFκB1, NFκB2 and RELA in patients with pterygium and controls." (PMID 31565648, 2018).
serous ovarian cancer (10 papers, 2014 to 2025). "What is interesting is that the ratio of NFKB1 to NFKB2 expression levels significantly decreased in high-grade serous ovarian cancer cells after incubation with all tested peptides." (PMID 35008474, 2021).
leprosy (9 papers, 2013 to 2023). Leprosy is a chronic infectious disease affecting primarily the skin and peripheral nervous system. "Similarly, 7 of the 9 SNPs significantly heterogeneous between T1R and leprosy were eQTLs in either whole blood, rs3774937 (NFKB1), rs10065637 (ANKRD55), rs11150589 (ITGAL) and rs2836878 (lncRNA ENSG00000235888) or multiple tissues, rs4664304 (LY75), rs113653754 (HLA-DQB1) and rs4768236 (LRRK2)." (PMID 28222097, 2017).
Peri-Implantitis (9 papers, 2017 to 2025). An inflammatory process with loss of supporting bone in the tissues surrounding functioning DENTAL IMPLANTS. "Exploration of available transcriptomic datasets revealed IL-6, NFKB1, and PIK3CG expression along with the IL-17 signaling pathway as top candidate molecular linkage mechanisms between peri-implantitis and T2DM." (PMID 31275749, 2019). "Three common or cross-talk genes; IL-6, NFKB1, and PIK3CG, were noted among the top 20 hub genes in the PPI networks of T2DM and peri-implantitis." (PMID 31275749, 2019). "Three hub genes (IL-6, NFKB1, and PIK3CG) had the highest degree in PPI networks of both peri-implantitis and T2DM." (PMID 31275749, 2019). "Among these top 20 hub genes, three genes (IL6, NFKB1, and PIK3CG) were common to peri-implantitis and T2DM, thus can be regarded as the potential cross-talk genes." (PMID 31275749, 2019). "In peri-implantitis, NFKB1 has been previously identified as a key candidate gene and is shown to regulate inflammation-induced osteoclastogenesis by regulating receptor activator of NF-κB ligand (RANKL)—mediated osteoclast formation and activation in peri-implantitis." (PMID 31275749, 2019).
primary biliary cirrhosis (9 papers, 2012 to 2023). "The MANBA/NFKB1 region was identified in previous studies as a disease susceptibility locus for primary biliary cholangitis (PBC) and a recent study found a decreased level of IgG galactosylation in PBC patients." (PMID 38149987, 2023). "We had recently used a similar approach to identify primary functional variants in the primary biliary cholangitis (PBC)-susceptibility gene loci NFKB1/MANBA22." (PMID 33574277, 2021). "These intronic markers in the NFKB1 gene are located in chromosome 4q24 and they have been strongly associated with primary biliary cirrhosis." (PMID 25397881, 2014).
schistosomiasis (9 papers, 2014 to 2024). An infectious disease caused by parasitic trematodes of the genus Schistosoma that colonize human blood vessels and release eggs that can cause granulomatous reactions leading to acute (swimmer's itch or acute schistosomiasis syndrome) or chronic disease. "Several genes dysregulated by either or both species of schistosomes have been linked to inflammation and schistosomiasis-associated disease but have not been associated with cancer, at least in a direct manner, e.g. Tumor Necrosis Factor (TNF) or Nuclear Factor Kappa B subunit 1 (NFK-B)." (PMID 31341177, 2019).
septic shock (9 papers, 2012 to 2022). Shock caused by infection; frequently caused by gram negative bacteria, although some cases have been caused by other bacteria, viruses, fungi, and protozoa; characterized by fever, chills, tachycardia, tachypnea, and hypotension. "In conclusion, hydrocortisone therapy in deletion allele carriers of the NFKB1 promoter polymorphism (-94ins/delATTG) is a strong and independent predictor for 30-day mortality of septic shock." (PMID 25133403, 2014).
prediabetes (8 papers, 2012 to 2025). "Significantly higher expression levels of these mRNAs, including NFKB1, were observed in the blood of patients with prediabetes and T2DM compared to healthy controls." (PMID 40508108, 2025). "In the current pilot study, the expressions of ZBP1, DDX58, NFKB1 and CHUK were significantly higher in the T2DM group compared to either healthy control or pre-DM patients, which may give us new predictive markers for the development of T2DM in prediabetes patients." (PMID 36139069, 2022).
Opportunistic infection (7 papers, 2015 to 2024). An infection that is caused by a pathogen that would generally not be able to cause an infection in a host with a normal immune system. "In our patients, mutations in NFKB1 and STAT3 also led to opportunistic infections, including Mycobacterium avium intracellulare, JC virus-induced progressive multifocal leukoencephalopathy, Pneumocystis jirovecii pneumonia, and Molluscum contagiosum." (PMID 27379089, 2016). "Intronic NFKB1 mutations were also observed in the patient’s father, who showed no clinical manifestations of repeated opportunistic infections." (PMID 39823049, 2024). "Here, we report a very rare case of recurrent opportunistic infections in a non-HIV-infected patient combined with mutations in complement component C6 and nuclear factor kB subunit 1 (NFKB1)." (PMID 39823049, 2024).
pelvic inflammatory disease (7 papers, 2016 to 2023). Pelvic inflammatory disease (PID) is an acute or chronic inflammation in the pelvic cavity. "The key target proteins for the SC and PS against pelvic inflammatory disease with dampness-heat stasis syndrome included vascular endothelial growth factor A (VEGFA), von willebrand factor (VWF), interleukin 6 (IL6), tumor necrosis factor (TNF) and nuclear transcription factor 1 (NFκB1)." (PMID 33424592, 2020).
plasma cell neoplasm (7 papers, 2010 to 2025). A clonal proliferation of immunoglobulin-secreting plasma cells. "The identification of the novel IGH::NFKB1 fusion gene in this case underscores the importance of molecular diagnostics in uncovering actionable genetic alterations in rare plasma cell neoplasms." (PMID 41200196, 2025).
gynecological cancer (6 papers, 2020 to 2025).
Hyperoxaluria (6 papers, 2019 to 2024). Increased excretion of oxalates in the urine. "In order to assess the inflammatory response elicited by hyperoxaluria in preglomerular arteries, RT-PCR was performed to assess the expression of NFκB1, MCP1, and TNFα." (PMID 35954150, 2022).
male infertility (6 papers, 2018 to 2024). The inability of the male to effect fertilization of an ovum after a specified period of unprotected intercourse. "In the light of these data; variations in NFKB1 gene, which has an impact on gene expressions and adhesion molecules including E-cadherin, would be affinitive candidate factors of male infertility risk." (PMID 29942932, 2018). "Moreover, ins/ins and del/del genotypes in the promoter region, NFKB1 is likely to play a role in the susceptibility to oligospermic male infertility in the context of low E-cadherin expression." (PMID 29942932, 2018). "However, in the literature, there are no studies that illuminate the relationship between oligospermic male infertility and promoter site variations of NFKB1 rs28362491." (PMID 29942932, 2018).
autism spectrum disorder (5 papers, 2016 to 2024). A spectrum of developmental disorders that includes autism, and Asperger syndrome. "SMARCA4 has been associated with MIA-related autism spectrum disorder, and the nuclear factor kappa B subunit 1 (NFKB1) enrichment is aligned with the low-level chronic inflammation and enhanced response to an inflammatory stimulus in a knockout mouse model." (PMID 36672818, 2022).
cocaine addiction (5 papers, 2019 to 2025). "Among up- and downregulated genes from the pathway hsa05030:cocaine addiction are genes JUN, GNAS, BDFN, and CDK5R1 (upregulated), and FOSB, NFKB1, CREB1 and PPP1R1B (downregulated)." (PMID 34947877, 2021).
myxoma (5 papers, 2015 to 2024). A benign soft tissue neoplasm characterized by the presence of spindle and stellate cells, lobulated growth pattern, and myxoid stroma formation. "Macrophages in myxoma were associated with the upregulation of NFKB1, PDGFC, and IL1B, as well as the downregulation of ATP5PB, HSPB1, and IFI27." (PMID 39090109, 2024).
pyoderma gangrenosum (5 papers, 2021 to 2025). An idiopathic, rapidly evolving, and severely debilitating disease occurring most commonly in association with chronic ulcerative colitis. "Monoallelic LOF variants of NFKB1 can predispose to uncontrolled inflammation including sterile necrotizing fasciitis or pyoderma gangrenosum." (PMID 36892687, 2023). "NFKB1 LOF may also lead to extreme pro-inflammatory cytokine production in association with necrotizing fasciitis or pyoderma gangrenosum." (PMID 36892687, 2023).
Rett syndrome (5 papers, 2016 to 2023). A severe neurodevelopmental disorder affecting the central nervous system. "Another study reinforces Gsk3β-mediated neuroinflammation, partially by enhancing nuclear factor kappa b subunit 1 (Nfkb1) signaling, where the inhibition of Gsk3β with the SB216763 inhibitor reduces Nfkb1 signaling and inflammation levels, in a mouse model of Rett syndrome." (PMID 35203447, 2022).
adenoid cystic carcinoma (4 papers, 2013 to 2022). A malignant tumor arising from the epithelial cells. "Also, people have detected a significant alteration in expression of NFKB1 in adenocystic carcinomas, which suggests that NFKB1 might be served as a target for innovative diagnostic and treatment programs." (PMID 30289891, 2018).
Pleural effusion (4 papers, 2008 to 2025). The presence of an excessive amount of fluid in the pleural cavity. "In addition, a trend towards significance was found for association of the NF-κB pathway related genes IL1B and NFKB1 with the occurrence of severe complications and for IL8 and NFKB2 with pleural effusion." (PMID 18398488, 2008). "Analysis of DEGs in Cycling GZMA and GZMA CD4 T cells from pleural effusion of HP and LCP revealed that seven transcription factors (MLLT3, KLF12, FOXP1, NFKB1, ZEB2, TOX, JAZF1) were upregulated in both cycling GZMA CD4 and GZMA CD4 cells in MPE of LCP." (PMID 40959273, 2025).
testicular cancer (4 papers, 2020 to 2024). A primary or metastatic malignant neoplasm that affects the testis. "No studies were found about these specific variants in testis or these genes in testicular cancer, but the role of IL1A, NFKB1 and XRCC1 have been reported in Sertoli cells and other essential factors for spermatogenesis." (PMID 35678683, 2022).
X-linked agammaglobulinemia (4 papers, 2019 to 2025). X-linked agammaglobulinemia (XLA) is a clinically variable form of isolated agammaglobulinemia, an inherited immunodeficiency disorder (see this term), and is characterized in affected males by recurrent bacterial infections during infancy. "For example, X-linked agammaglobulinemia (caused by mutations in BTK) is probably not eight times more prevalent than, e.g., the autosomal-dominant CTLA4-(haplo)insufficiency or NFKB1-(haplo)insufficiency." (PMID 41347188, 2025).
colonic polyps (3 papers, 2015 to 2024). "Wild‐type and Nfkb1−/− mice developed a median of four colonic polyps per animal (PPA)." (PMID 25727407, 2015).
echinococcosis (3 papers, 2020 to 2024). A parasitic infection caused by tapeworm larvae of Echinococcus. "Studies conducted on other hydatid disease foci have also shown high expression of Nfkb1 around the foci, suggesting its involvement in the establishment of parasite immune evasion." (PMID 38655088, 2024). "Related studies have reported that NFKB1 is the core TF regulating hydatidosis, and it may participate in the inflammatory process of hydatidosis." (PMID 32596042, 2020). "NFKB1 significantly regulates 4 dysfunction modules of human hydatidosis." (PMID 32596042, 2020).
Pneumocystis (3 papers, 2016 to 2024). "Furthermore, upon analysis, we found a number of TFs either down- or upregulated that have been previously implicated in Pneumocystis AM interactions, including previously upregulated TFs Irf1, and Nfkb1, and in the murine Pneumocystis pneumonia (PCP) model, we observed the downregulation of Egr1." (PMID 34066663, 2021).
sensorineural hearing loss (3 papers, 2014 to 2023). "Regarding RNF31 variants involved in linear ubiquitination of NF-κB signaling components, regulatory variants in the NFKB1 gene have been reported to modify hearing outcomes in patients with MD and unilateral sensorineural hearing loss." (PMID 37273692, 2023).